RPS6 (ribosomal protein S6)
Diseases named in the same sentence as RPS6 in open-access papers (continued):
Sharing a sentence is not in itself a finding about the gene and the disease.
leukemia (13 papers, 2014 to 2025). A malignant (clonal) hematologic disorder, involving hematopoietic stem cells and characterized by the presence of primitive or atypical myeloid or lymphoid cells in the bone marrow and the blood. "The activation of the mTOR pathway was confirmed in Kmt2d‐deficient leukemia cells, as shown by Western blots with antiphosphorylated ribosomal protein S6, a substrate of direct mTORC1 target S6K1." (PMID 37142882, 2023). "Ribosomal protein S6 (RPS6) has been reported to be associated with cancers, such as leukemia, pancreatic cancer, and non-small cell lung cancer." (PMID 35883585, 2022). "Several PI3K/AKT/MTOR pathway genes were identified to affect cell proliferation in the shRNA screen (e.g. PIK3CD, AKT2, AKT1, RPS6) confirming our previous data about PI3K/AKT/MTOR activation in mouse E2A-PBX1+ leukemia cells." (PMID 35794338, 2022). "Recent studies have revealed that hyperphosphorylation of RPS6 and RPS6 expression may predict malignant phenomena in several cancers, such as non-small cell lung cancer and leukemia, etc.." (PMID 34831193, 2021). "The genes in the leukemia cell line term were AFDN (alias MLLT4, chromosome 1, WHWT), KLF3 (chromosome 3, LR), RPS6, (chromosome 5, LR), and FCER2, MCOLN1, and PRAM1 on chromosome 20 (GSD)." (PMID 36482174, 2022). "Employing the MAGeCK algorithm, this focused CRISPR screen unveiled COX4I1 (encoding Cytochrome c oxidase subunit 4 isoform 1) as a top essential gene in leukemia cells, alongside five previously reported leukemia essential genes (MYC, RPS6, CCND3, GAB2, and AURKB)." (PMID 39716856, 2025). "Altogether, our data reveal that a syntenin‐deficient environment may ultimately lead to the activation of EEF1A2/AKT/RPS6 molecular pathways in AML cells, stimulating protein synthesis and enhancing cell survival, advantages educating the leukemia to become more aggressive." (PMID 37819151, 2023).
pancreatic cancer (13 papers, 2015 to 2023). "While it was until recently that rpS6 had been demonstrated to be the decisive factor for the initiation of pancreatic cancer." (PMID 30902093, 2019). "Deletion of ribosomal protein S6 renders the mice resistant to chemically or genetically induced pancreatic cancer precursor lesions." (PMID 30305629, 2018). "The development of these pancreatic cancers in these models is associated with activation of AKT and RPS6." (PMID 26436951, 2015). "Increased phosphorylation of AKT and RPS6 was identified within pancreatic cancers by Immunohistochemistry (IHC) compared with Pc0 mice." (PMID 26436951, 2015). "Exceptional expression or activation of rpS6 has been found in multiple sclerosis, pancreatic cancer, squamous cell carcinoma of the oral cavity, and even the brain areas with acute ketamine-induced neuroplasticity." (PMID 26490682, 2015). "We employed a rabbit monoclonal antibody specific for RPS6(Ser235P/Ser236P) and high content microscopy to quantify rpS6 phosphorylation in the pancreatic cancer cell line MIA PaCa-2." (PMID 25790369, 2015). "In our study, the induction of autophagy in pancreatic cancer cells was independent of the inhibition of RPS6 phosphorylation status, indicating that other molecular mechanisms may be involved." (PMID 37568682, 2023).
ovarian carcinoma (11 papers, 2016 to 2025). A malignant neoplasm originating from the surface ovarian epithelium. "The observation that loss of either CDR2L or RPS6 causes similar effects on the cell cycle in ovarian cancer cells further supports an association between the two proteins." (PMID 38802745, 2024). "In this study, we demonstrated that RPS6 is significantly upregulated in ovarian cancer, and that its expression is significantly associated with clinical stage and pathological grade." (PMID 32862831, 2020). "Similarly, reduction of levels of the ribosomal protein RPS6 in ovarian cancer cells caused downregulation of CDK2, CDK4, CDK6, cyclin E, and cyclin D1, thereby blocking the transition from G0/G1 to S phase and suppressing cell proliferation." (PMID 38802745, 2024). "Moreover, the OS rate of the group with high RPS6 expression was significantly shorter than that of the group with low RPS6 expression, indicating that RPS6 levels are negatively associated with survival in patients with ovarian cancer." (PMID 32862831, 2020). "Consistently, the G0/G1 checkpoint regulators, such as cyclin D1, cyclin E, CDK2, CDK4, CDK6, and p-RB, are diminished by RPS6-KD in ovarian cancer cells." (PMID 35008473, 2021). "It has been reported that the transfection of ovarian cancer cells with RPS6-siRNA reduces the activities of glutaminase (GLS) and glutamate dehydrogenase (GDH), leading to a reduction in glutamine-induced proliferation of the cells." (PMID 35008473, 2021). "RPS6-KD also inhibits the proliferation and long-term colony formation of the ovarian cancer cell lines SKOV-3 and HO-8910." (PMID 35008473, 2021). "In follow-up experiments, we explored the specific means by which RPS6 knockdown inhibits ovarian cancer cell proliferation." (PMID 32862831, 2020). "The specific regulatory mechanism mediated by RPS6 in ovarian cancer will be the subject of further studies in the future." (PMID 32862831, 2020). "Lentiviral vector-mediated transfection was used to determine the effect of RPS6 silencing in ovarian cancer cells." (PMID 32862831, 2020). "Knockdown of RPS6 inhibited ovarian cancer cell proliferation, and this effect was enhanced over time." (PMID 32862831, 2020). "The role of RPS6 in ovarian cancer was also assessed by silencing its expression in ovarian cancer cell lines and conducting functional assays." (PMID 32862831, 2020). "Knockdown of RPS6 reduced the proliferation of ovarian cancer cell lines SKOV-3 and HO8910, and inhibit the migration and invasion ability." (PMID 32862831, 2020). "Moreover, we showed that PARP16, a tail-anchored endoplasmic reticulum-associated protein, is a MART that MARylates RPS6 and RPL24 in ovarian cancer cells to control the loading of mRNAs on ribosomes and their translation." (PMID 39760726, 2025). "The small ribosomal protein RPS6 and phosphorylated-RPS6 also have increased abundance in many cancers, such as ovarian cancer, esophageal squamous cell carcinoma, and non-small cell lung cancer and promotes invasive activity (Kimet al., 2013;Yanget al., 2020)." (PMID 38628976, 2023). "The migration and invasion of these ovarian cancer cells are also reduced by RPS6-KD." (PMID 35008473, 2021). "Knockdown of RPS6 resulted in an inhibition of ovarian cancer cell proliferation and invasion." (PMID 33256002, 2020). "Nevertheless, the specific function of RPS6 in the development of ovarian cancer remains unclear and warrants further investigation." (PMID 32862831, 2020). "Our research here provides evidence that high expression of RPS6 is a molecule event in the development of ovarian cancer and may therefore be a novel and promising drug target for anticancer therapies." (PMID 32862831, 2020). "Therefore, RPS6 may represent a novel marker and/or therapeutic target for patients with ovarian cancer." (PMID 32862831, 2020).
ovarian carcinoma (continued). "In this study, RPS6 knockdown resulted in decreased Cyclin E, CDK2, Cyclin D1, CDK4, and CDK6 levels, and reduced Rb phosphorylation, thus hindering the transition from G0G1 to S phase, causing most cells to be blocked in G0G1 phase, thereby inhibiting ovarian cancer cell growth." (PMID 32862831, 2020). "In ovarian cancer cells, PARP16 uses NAD+ produced by the cytosolic NAD+ synthase NMNAT-2 to MARylate RPS6 and RPL24." (PMID 39760726, 2025). "Ribosomal protein S6 (RPS6) is a ribosomal protein involved in the ribosomal 40S subunit, but its biological role in epithelial ovarian cancer (EOC) is still unknown." (PMID 32862831, 2020). "Moreover, RPS6 is upregulated in various human cancers relative to normal tissues; however, the role of RPS6 in ovarian cancer has not been fully elucidated to date." (PMID 32862831, 2020). "Notably, expression levels of RPS6, RPL12, CTNNB1, RPL7, RPS2, and CALM3 did not have any impact on the survival of ovarian cancer patients." (PMID 39309198, 2024).
colorectal cancer (10 papers, 2014 to 2024). A primary or metastatic malignant neoplasm that affects the colon or rectum. "RPS6 was associated with drug resistance in colorectal cancer, but this gene may be responsible for drug resistance in EOC." (PMID 30970615, 2019). "To this end, we knocked down RPS3, RPS6 and RPS20 as well as RPL7 in human HCT116 colorectal cancer cells that are either WT or deficient for p5343." (PMID 39609413, 2024). "Further, in the colorectal cancer study, aspirin decreases RpS6 expression compared to RpL11; this misbalance in ribosomal proteins impairs ribosome maturation." (PMID 36875757, 2023). "Increased expression of ribosomal protein genes including rpS3, rpS6, rpS8, rpS12 and rpL5 has been reported in colorectal cancer." (PMID 32973493, 2020). "MJ-56, a new novel anti-metastasis drug, even showed the p-rpS6-mediated invasion inhibition effects in colorectal cancer cells." (PMID 26490682, 2015). "Additionally, serpinA3 upregulation resulted in increased phosphorylation of both AKT and its downstream target ribosomal protein S6 (rpS6), which contributed to colorectal cancer development." (PMID 39634266, 2024). "For example, the expression of RPL5, RPS3, RPS6, RPS8, and RPS12 in colorectal cancer was higher than that in normal colorectal mucosa." (PMID 33584809, 2020). "In colorectal cancer, the elevation of some specific small RPs, including RPS3, RPS6, RPS8, and RPS12, increases ribosome biogenesis and possibly leads to the activation of extra-ribosomal functions such as DNA replication, RNA splicing and modification, and cell growth." (PMID 35159381, 2022).
gastric cancer (10 papers, 2017 to 2023). A primary or metastatic malignant neoplasm involving the stomach. "Previous work proved that RPS6 acted as anti-HER2 drug-resistant factors in HER2-amplified gastric cancer." (PMID 35281852, 2022). "The PI3/AKT/mTOR/RPS6 pathway confers resistance in HER2-Amplified Gastric Cancer through the stimulation of the nuclear factor erythroid 2-related factor 2 (NRF2), a factor involved in chemo- and radioresistance in different tumors." (PMID 34873618, 2021). "Several studies have shown that proteins involved in ribosome biogenesis play a key role in radioresistance and chemoresistance in various cancer types, and in particular, the involvement of RPS6 in the resistance to trastuzumab and lapatinib has been demonstrated in gastric cancer models." (PMID 38203378, 2023). "In HER2-Amplified Gastric Cancer, RPS6 seems to be involved in resistance to therapy." (PMID 34873618, 2021). "A previous study has observed that reducing the phosphorylation of RPS6 could have an influence on the sensitivity to MEK inhibition in gastric cancer cells." (PMID 28232943, 2017). "Gambardella and coworkers found that NRF2 amplified the resistance to anti-HER2 drugs through the PI3K/AKT/mTOR/RPS6 pathway, and that ribosomal protein S6 (RPS6) inhibition decreased NRF2 expression and restored sensitivity in HER2-amplified gastric cancer." (PMID 34070502, 2021). "In human epidermal growth factor receptor 2 (HER2)-amplified gastric cancer (GC) cell lines with resistance to the HER2 inhibitors (HER2is) lapatinib and trastuzumab, RPS6-KD reduced the cell viability and the cellular resistance to HER2is." (PMID 35008473, 2021).
non-small cell lung carcinoma (10 papers, 2015 to 2024). A group of at least three distinct histological types of lung cancer, including non-small cell squamous cell carcinoma, adenocarcinoma, and large cell carcinoma. "Abnormal expression of RPS6 or phosphorylated-RPS6 has been detected in vulvar squamous cell carcinoma, cervical cancer, oral squamous cell carcinoma, non-small cell lung cancer, renal cell carcinoma, esophageal squamous cell carcinoma." (PMID 32862831, 2020). "Consistent with our results, studies showed that RPS6 was overexpression in non-small cell lung cancer, esophagus squamous cell carcinoma, pancreatic neuroendocrine tumors and sarcoma." (PMID 32862831, 2020). "RPS6 overexpression portends reduced survival for patients with renal carcinoma and hyperphosphorylation of Rps6 confers poor prognosis in non-small cell lung cancer." (PMID 31660150, 2019). "Interestingly, overexpression of rpS6 and phosphorylation of rpS6 promoted the proliferation, migration, and invasion in non-small cell lung cancer cells." (PMID 28096814, 2016).
prostate carcinoma (10 papers, 2014 to 2025). A carcinoma that arises from epithelial cells of the prostate gland. "In prostate cancer, as a key metabolite of Phellodendron amurense bark extract, palmatine synergistically inhibits the rpS6/NF-κB/FLIP signaling axis along with other bioactive metabolites, effectively reducing tumor invasiveness." (PMID 40786032, 2025). "Since RPS6-KD induced PD-L1 expression and immune-resistance in breast and prostate cancer cells, further studies will clarify the potential role of p-RPS6 in immuno-oncological regulation." (PMID 35008473, 2021). "In prostate cancer cells, the ribosomal protein S6, a downstream target of p70S6K and the Akt/mTOR signaling cascade was identified as a potential target of palmatine." (PMID 31027283, 2019). "Furthermore, palmatine prevents prostate cancer cell invasion by suppressing ribosomal protein S6 (rpS6)/NF-κB activation and downstream FLICE-like inhibitory protein (FLIP) gene expression." (PMID 40786032, 2025). "EphB4 knockdown lowered EphB4 and the PI3K downstream markers pAKT (Thr308) and phosphorylated ribosomal protein S6 (pS6, Ser235/Ser236) in PC3 and castrate-resistant prostate cancer cell lines C4-2B and 22Rv1." (PMID 40044981, 2025). "In prostate cancer cells, a possible target for PLT was receptor tyrosine kinase, such as S6 ribosomal protein (rpS6), a key regulator of protein synthesis and a downstream effector of the Akt/mTOR/p70S6K signaling pathway." (PMID 34684834, 2021). "Again, there was clear positive correlation between the expression of LARP1 and the RP proteins (e.g. RpS6) but not between LARP1 protein and RpS6 mRNA in prostate cancer and normal cells." (PMID 28650797, 2017). "Furthermore, we show that two PI3K pathway-regulated protein activities, pS6 (RPS6-phosphoserines 235/236) and pPRAS40 (AKT1S1-phosphothreonine 246), correlate with prostate cancer lethal outcome as well (individual marker hazard ratios of 2.04 and 2.03, respectively)." (PMID 25075204, 2014).
glioma (9 papers, 2015 to 2025). A benign or malignant brain and spinal cord tumor that arises from glial cells (astrocytes, oligodendrocytes, ependymal cells). "Additionally, sCPE diminishes glioma cell migration associated with a negative regulation of Rac1 signaling via RPS6, since both inhibition of mTOR and stimulation of Rac1 results in a reversed effect of sCPE on migration." (PMID 28978054, 2017). "In this line of studies, we found that the expression of RPS6 is correlated with the grade of glioma." (PMID 35883585, 2022). "The immunohistochemical analysis showed significant upregulation of RPS6 expression in high-grade glioma compared with that in low-grade gliomas." (PMID 35883585, 2022). "More importantly, our recent study revealed that intrinsic RPS6 promotes stem-like characters in glioma cells." (PMID 34831193, 2021). "Immunohistochemical staining analysis of RPS6 phosphorylation in glioma patient tissues clearly showed that RPS6 phosphorylation (pRPS6) was more strongly detected in high-grade glioma (grade." (PMID 34831193, 2021). "The glioma-derived extrinsic ribosome incorporation promoted GBM-RICCS formation in glioma through intrinsic RPS6 phosphorylation." (PMID 34831193, 2021). "Here we show that sCPE activates mTORC1 signaling in glioma cells detectable by phosphorylation of its downstream target RPS6." (PMID 28978054, 2017). "We observed strong signals for phospho-RPS6 (Ser235/236), phospho-RPS6 (Ser240/244) and phospho-4EBP1 (Thr37/46) in the glioma cell line LNT-229 cultured in DMEM (glucose levels 25 mM) containing 10% serum." (PMID 25993328, 2015). "We found that phospho-RPS6 (Ser235/236), phospho-RPS6 (Ser240/244) and phospho-4EBP1 (Thr37/46) can be strongly detected in SEGAs as well as in malignant tumors of the central nervous system." (PMID 25993328, 2015). "Moreover, phosphorylated RPS6 levels are elevated in high-grade gliomas, suggesting potential context-dependent or extra-ribosomal roles." (PMID 41589302, 2025). "Furthermore, RPS6 phosphorylation on Ser235-Ser236 in glioma tissues was observed in high-grade gliomas." (PMID 36994107, 2023). "Our data suggest that the glioma-derived extrinsic ribosome may serve as a key trigger for GSCs development through intrinsic RPS6 phosphorylation." (PMID 34831193, 2021). "In addition, the glioma-derived extrinsic ribosome promoted GBM-RICCS formation in glioma, suggesting potential biological roles of extrinsic ribosomal proteins through intrinsic RPS6 phosphorylation." (PMID 34831193, 2021). "Furthermore, we also revealed that ribosome including RPS6 played crucial roles in stem-like characters in glioma cells in GBM patients." (PMID 34831193, 2021). "Moreover, consistently, glioma-derived extrinsic ribosome also promoted GBM-RICCS formation through intrinsic RPS6 phosphorylation." (PMID 34831193, 2021). "Moreover, in accordance with the results using prokaryotic ribosome, GBM-RICCS formation by the glioma-derived extrinsic ribosome was markedly suppressed by RPS6 kinase inhibitor (PF47018671)." (PMID 34831193, 2021). "Although our results showed that extrinsic ribosome might induce stem cell characters in glioma cells through intrinsic RPS6 phosphorylation, the biological and clinical significance of the incorporation of ribosome into glioma cells are still unknown." (PMID 34831193, 2021). "Moreover, in glioma patients, RPS6 phosphorylation was dominantly observed in high-grade glioma tissues, and predominantly upregulated in GSCs niches, such as the perinecrosis niche and perivascular niche." (PMID 34831193, 2021). "Hence, we propose, that sCPE enhances RPS6 activation via mTOR signaling and reduces aerobic glycolysis thereby constituting a novel modulator of glioma cell migration." (PMID 28978054, 2017). "Altogether, we were able to detect a cross-talk between sCPE, RPS6, Rac1 and glioma cell migration." (PMID 28978054, 2017).